ENSG00000238316
Synonyms: LOC124904813
Gene: Small nucleolar RNA gene on chromosome 1 (26,642,286 to 26,642,389, reverse strand). Ensembl gene ENSG00000238316.
Gene Ontology:
Biological process: RNA processing
Cellular component: nucleolus
Homologues: Orthologues: rat LOC120102746 (79% identical), rat LOC120100483 (68% identical). Paralogues in human: SNORD13P1 (84% identical), SNORD13 (81% identical), SNORD13D (81% identical), SNORD13P3 (78% identical), SNORD13E (76% identical).